KIF16B (kinesin family member 16B)
Description:
Plus end-directed microtubule-dependent motor protein involved in endosome transport and receptor recycling and degradation. Regulates the plus end motility of early endosomes and the balance between recycling and degradation of receptors such as EGF receptor (EGFR) and FGF receptor (FGFR). Regulates the Golgi to endosome transport of FGFR-containing vesicles during early development, a key process for developing basement membrane and epiblast and primitive endoderm lineages during early postimplantation development.
Synonyms: C20orf23; SNX23; FLJ20135; dJ971B4.1; KISC20ORF
Tractability: PROTAC: ubiquitination databases record sites on it.
Gene: Protein-coding gene on chromosome 20 (16,272,104 to 16,573,448, reverse strand). Ensembl gene ENSG00000089177.
Subcellular location: Cytoplasm, cytoskeleton; Early endosome membrane; Cytoplasm; Cytoplasm, cytoskeleton, spindle
Subcellular location (Human Protein Atlas): Mitochondria
Pathways (Reactome):
Hemostasis: Kinesins
Vesicle-mediated transport: COPI-dependent Golgi-to-ER retrograde traffic
Gene Ontology:
Molecular function: phosphatidylinositol-3,4,5-trisphosphate binding; phosphatidylinositol-3,4-bisphosphate binding; phosphatidylinositol-3,5-bisphosphate binding; phosphatidylinositol-3-phosphate binding; plus-end-directed microtubule motor activity; ATP binding; microtubule binding; microtubule motor activity; phosphatidylinositol binding
Biological process: early endosome to late endosome transport; epidermal growth factor receptor signaling pathway; receptor catabolic process; regulation of receptor recycling; endoderm development; fibroblast growth factor receptor signaling pathway; formation of primary germ layer; Golgi to endosome transport; vesicle transport along microtubule; cell surface receptor protein tyrosine kinase signaling pathway; intercellular transport; microtubule-based movement; vesicle-mediated transport
Cellular component: cytoplasm; early endosome; early endosome membrane; endosome; spindle; kinesin complex; cytoplasmic vesicle; cytoskeleton; cytosol
Genetic constraint (gnomAD): Loss-of-function variants: 65 observed, 101.69 expected, observed/expected ratio (o/e) 0.64, 90% interval 0.52 to 0.79. The upper end of that interval is the gene's LOEUF score, 0.79, which puts it in group 3 of 6, group 1 being the genes least tolerant of losing a copy. Missense variants: 1,122 observed, 1,265.5 expected, observed/expected ratio (o/e) 0.89, 90% interval 0.84 to 0.93. Synonymous variants: 431 observed, 482.07 expected, observed/expected ratio (o/e) 0.89, 90% interval 0.82 to 0.97.
Homologues: Orthologues: rabbit KIF16B (81% identical), pig KIF16B (80% identical), zebrafish kif16ba (59% identical), zebrafish kif16bb (33% identical), zebrafish stard9 (30% identical). Paralogues in human: KIF1A (30% identical), KIF1B (29% identical), KIF13B (28% identical), KIF14 (28% identical), KIF13A (27% identical), KIF1C (25% identical), KIF21A (19% identical), KIF21B (19% identical), CENPE (18% identical), KIF4A (18% identical), KIF4B (18% identical), KIF27 (18% identical), and 29 more.
Diseases named in the same sentence as KIF16B in open-access papers:
KIF16B is named in the same sentence as 11 diseases in open-access papers, as found by Europe PMC text mining. Sharing a sentence is not in itself a finding about the gene and the disease. The quoted sentences say what the papers report.
autosomal recessive intellectual disability syndrome (1 paper, 2022). "Bi-allelic variants in the KIF16B gene may be linked to autosomal recessive intellectual disability syndrome." (PMID 36310845, 2022).
Intellectual disability (1 paper, 2025). "KIF16B, KIF4A, and KIF5C mutations were found in clinical samples, and patients showed varying degrees of intellectual disability." (PMID 40964093, 2025).
lung carcinoma (1 paper, 2025). "KIF16B expression was also implicated in the growth of pre-metastatic tumours in human models of the lung-to-brain metastasis, and low mRNA expression of KIF16B was associated with poor disease-free survival in LUAD patients, indicating its prognostic significance in lung cancer." (PMID 40002279, 2025).
cancer (10 papers, 2014 to 2025). A tumor composed of atypical neoplastic, often pleomorphic cells that invade other tissues. "Accordingly, a group of genes that we identified by ChIP-seq and that responded differentially to GATA3 (for example, BMP2, ERBB4 and KIF16B) are linked to proliferation and maintenance of normal or cancer stem cells." (PMID 25410484, 2014). "Recycling of the metalloproteinase MT1-MMP by the motor KIF16B regulates 3D invasion of macrophages, and also co-invasion of cancer cells, pointing to a role of KIF16B in the tumor microenvironment." (PMID 37696580, 2023). "Moreover, we demonstrate that the KIF16B-driven pathway in macrophages is critical for their matrix-degrading and invasive abilities, and notably also for co-invasion of cancer cells." (PMID 37696580, 2023). "Importantly, depletion of KIF16B in primary macrophages also reduces the co-invasion of cancer cells from tumor spheroids, pointing to the KIF16B-driven recycling pathway in macrophages as an important regulatory element of the tumor microenvironment." (PMID 37696580, 2023).
neurologic disease (1 paper, 2015). "SAFB1 mediated isoform-specific changes in ANK3, ANKS1B, SAP97 (DLG1), ADD2, KIF16B, and ELK3, as well as in genes linked to the cytoskeleton and/or synaptic function and the aetiology of neurologic disease." (PMID 26694817, 2015).
KIF16B also shares sentences with these, for which no sentence is quoted: tumor (4 papers); adenocarcinoma (1); amyotrophic lateral sclerosis (1); B‐cell lymphoma (1); gastric cancer (1); myeloma (1).